HGF (hepatocyte growth factor)
Diseases named in the same sentence as HGF in open-access papers (continued):
Sharing a sentence is not in itself a finding about the gene and the disease.
infection (continued). "However, in the case of LY294002 treatment, more significant suppression in osteogenic differentiation was observed in cells with rAd-HGF infection (p < 0.05), which is as an even more obvious situation when compared with DMSO-treated hBMSCs infected with rAd-HGF (p < 0.001)." (PMID 29510550, 2018). "Our results embody the hypothesis that HGF produced by infection-activated Kupffer cells, sensitizes primary hepatocytes to engage a mitochondrial-independent apoptosis program in parasitized cells with established EEFs, potentially overcoming parasite strategies to block spontaneous apoptosis." (PMID 28220125, 2017). "We ask whether HGF secreted by Kupffer cells could impair hepatocyte infection in vitro." (PMID 28220125, 2017). "Infection with human cytomegalovirus (HCMV) has been associated with impaired differentiation of cytotrophoblasts down the invasive pathway, specifically dysregulating the response to mitogens including epidermal growth factor (EGF) and hepatocyte growth factor (HGF)." (PMID 23116176, 2012). "Early infection analysis showed eight markers that were elevated (padj<0.05) in the early infection group compared to the unexposed group, namely TGF-α, HGF, FGF-19, TNFSF14, TRAIL, RAGE-binding protein EN-RAGE, uPA and IL18R1." (PMID 41510260, 2025). "Several host pathways were identified as pro-viral or pro-inflammatory during different infection, such as PI3K/Akt, JAK/STAT, and mTOR, and among them the hepatocyte growth factor (HGF) receptor tyrosine kinase c-Met was especially notable." (PMID 40948770, 2025). "Thus, in addition to the established literature on HGF/Met and CagA interactions, our findings provide novel insights into how H. pylori infects its host through the HGF/Met-OipA interaction, further reinforcing the potential of HGF/Met as a therapeutic target for this infection." (PMID 39471168, 2024). "Hepatocyte growth factor (HGF) is secreted by the transmigrated hepatocytes, which bind the c-MET receptor and makes the hepatocyte vulnerable to infection by rearranging the host cell’s actin cytoskeleton." (PMID 37242305, 2023). "We then assessed if the level of HGF, the only known ligand for c-MET, was regulated at the site of infection." (PMID 35041723, 2022). "Among others, we identified HGF, TWEAK, MMPs and TNFα as proteins that still remain enhanced after the infection phase of the disease." (PMID 36405747, 2022). "During active infection, IFNα, IP10, IL6 and HGF showed a pleiotropic effect on several immune cells (top)." (PMID 34867943, 2021). "Then, we performed time-of-addition experiments, adding 50 nM HGF before, during, and after rLCMV/LASVGP infection." (PMID 32781509, 2020). "Cytokines GM-CSF, GRO-α, I-309, IL-1β, IL-6, MCP-1, MCP-2, TNF-α, thrombopoietin, BLC, Flt-3 ligand, HGF, IP-10, MIF, and MIP-3α were elevated by ≥1.5 fold relative to mock infection in both independent biological replicates of the cytokine array." (PMID 31536604, 2019). "Unlike what was observed for inflammatory cytokine content, soluble proangiogenic factors assayed (FGF-2, HGF, and ANGPT-2) were constitutively expressed in the UI corneas and did not change as a result of VEH or AP20187 treatment following infection." (PMID 28903153, 2017). "Upon further investigation, we found that specific cytokines, chemokines and growth factors could be correlated with subsequent infection: IL‐10, IL‐31, ENA‐78, fractalkine, MCP‐2, HGF and MMP‐1." (PMID 40766049, 2025). "Furthermore, increased fold change in the chemokines ENA‐78 (P = 0.0226), fractalkine (P = 0.0052) and MCP‐2 (P = 0.0011) and growth factors HGF (P = 0.0197) and MMP‐1 (P = 0.0407) were also correlated with subsequent infection." (PMID 40766049, 2025). "In the study, we showed increased circulating concentrations of 47 inflammatory proteins in patients with severe infection compared to healthy controls, with the most robust increase in the circulating concentration observed for TNFSF14, OSM, CCL23, IL-6, and HGF." (PMID 36209073, 2022).
infection (continued). "Increased HGF has been found in plasma during infection in both septic and nonseptic patients, where early phase septic patients displayed elevated levels of TNF and IL‐10,24 signifying an active inflammatory response." (PMID 35285058, 2022). "Nevertheless, experimental infection of different hepatoma cell lines showed that the induction of HGF signaling did not improve Plasmodium falciparum invasion and was not crucial for infection by P. falciparum or Plasmodium yoelii." (PMID 28220125, 2017). "In contrast, infection with adenovirus encoding RCAN1.1 did not stimulate migration and inhibited VEGF-mediated migration, with no apparent effect on HGF-stimulated migration." (PMID 28271280, 2017). "Two days after infection, no change in c-Met expression was apparent (Fig. 3Ai & Bi) whilst a 1.7 ± 0.3-fold (P < 0.01) increase in c-Met phosphorylation was detected in HGF-over-expressing cells compared to controls (Fig. 3Aii & Bii)." (PMID 21920521, 2011). "At the same time, infection itself does not activate EMT genes (or may even suppress HGF, FOXC2, and VEGFR genes) and is not able to induce an invasive phenotype formation." (PMID 32899940, 2020). "Results of the WST-8 assays indicated that in growth medium, relative lower doses of HGF obtained by rAd-HGF infection at MOI = 10 or 50 could not significantly promote cell growth compared with the effects of rAd-Ctrl." (PMID 29510550, 2018). "It has been reported that HGF and its mRNA localize exclusively to NPCs in the liver, and we have confirmed that expression of Hgf mRNA in primary hepatocytes was not detectable, irrespective to infection with P. berghei (data not shown)." (PMID 28220125, 2017). "Moreover, the prometastatic effect of HGF on MDA-MB-436 xenografts was tremendously alleviated by infection with PKCζ-shRNA but not GFP-shRNA." (PMID 22242160, 2012). "Here we identified that CRP was the best predictor of disease severity among our investigated biomarkers, with suPAR levels being correlated with Delta infection, while LDH, sTREM-1 and HGF proved to best discriminate between survivors and non-survivors." (PMID 37388734, 2023). "Other cytokines such as FGF-Basic, HGF, MIG, and Eotaxin were not uniformly altered within groups, but specific animals experienced changes in those cytokines following infection." (PMID 34855915, 2021).
cardiovascular disease (23 papers, 2011 to 2025). "Their data indicated that an improvement in PA levels is associated with reduced HGF levels and cardiovascular disease (CVD) development." (PMID 38202116, 2023). "Given that the leading cause of death by NASH is cardiovascular diseases, targeting of the HGF-MET pathway should have beneficial effects on both liver and heart." (PMID 30083132, 2018). "Relevant to cardiovascular disease, HGF has previously been demonstrated to exert potent mitogenic effects on the endothelium, thereby promoting development of collateral blood vessels, which improves tissue perfusion in patients with atherosclerotic disease." (PMID 37809892, 2023). "In fact, HGF is being explored as an anti-fibrotic therapeutic agent in pulmonary and cardiovascular disease." (PMID 28114331, 2017). "HGF has been shown to play an important role in the pathogenesis of fibrotic cardiovascular disease and myocardial protection against ischemia/reperfusion injury." (PMID 23560074, 2013). "Given that HGF can suppress the risk of cardiovascular disease which is the leading cause of death in NASH patients, exogenous HGF administration may be a favorable option for the treatment of NAFLD." (PMID 30083132, 2018). "Moreover, a strong correlation was observed between the total bilirubin and the HGF levels in the present study, which signifies that elevation in serum HGF level was directly related to the severity of cardiovascular disease." (PMID 24642599, 2014). "HGF may also have enormous therapeutic potential for hepatic and renal disorders, in addition to cardiovascular diseases." (PMID 21512580, 2011). "Given the clinical relevance of atrial thrombus formation as a frequent complication in cardiovascular disease, we further examined whether AngIV affects expression of HGF or c-MET and whether it regulated c-MET phosphorylation in atria of mice after 30 days of AngIV administration." (PMID 40028176, 2025). "Hepatocyte growth factor (HGF) and its receptor Mesenchymal-epithelial transition factor (Met), which was originally found to be a potent mitogen that promotes hepatocyte growth and liver regeneration, are now proposed to have prominent roles in the cardiovascular diseases." (PMID 30594174, 2018). "Also HGF is not related to IMT, reinforcing the finding that this growth factor as well as spleen play a role in the advanced stage of cardiovascular disease and not in the early one." (PMID 31547124, 2019).
cerebral artery (13 papers, 2004 to 2023). "Studies in both humans and animals showed elevated levels of HGF in the systemic circulation associated with different liver pathologies." (PMID 26090463, 2015). "In a model of middle cerebral artery occlusion, HGF administration alone not only reduced glial scar tissue and thickness but promoted synaptogenesis and angiogenesis." (PMID 34955750, 2021). "HGF immunostaining was found in 80% (12 of 15) of liver tissue in colorectal liver metastatic patients and in all liver specimens taken from benign tumor patients." (PMID 14960204, 2004). "Moreover, HGF-expressing mesenchymal stromal cells were more efficient in a rat transient middle cerebral artery occlusion model compared to unmodified cells." (PMID 31238604, 2019). "Following transient middle cerebral artery occlusion (tMCAO), treatment with HGF/AAV-transduced DPSCs (HGF-DPSCs) was more effective than with untransduced DPSCs, as demonstrated by the attenuation of brain damage and improvement in neurological recovery." (PMID 35453487, 2022).
neurodegenerative disease (12 papers, 2014 to 2024). A disorder of the central nervous system characterized by gradual and progressive loss of neural tissue and neurologic function. "Understanding the multifaceted role of hepatocyte growth factor (HGF) in neuroprotection and repair across various neurodegenerative diseases is paramount for advancing therapeutic interventions." (PMID 39457044, 2024). "Gothelf and collaborators demonstrated that the CM derived from neurotrophic factor-secreting MSCs was enriched with BDNF, VEGF-A, and HGF and has been used effectively to have protective effects in several animal models of neurodegenerative diseases." (PMID 35055049, 2022). "HGF has been investigated as a therapeutic agent alone as well as in combination with cellular therapies for CNS injury and neurodegenerative disease, most notably for its neurotrophic and regenerative capacity." (PMID 34955750, 2021). "Hepatocyte growth factor (HGF) plays a role in neuronal survival and development, and has been implicated in neurodegenerative diseases." (PMID 34615471, 2021). "HGF is a potent neurotrophic factor involved in the development of the nervous system and exhibits a therapeutic effect in various neurodegenerative diseases." (PMID 32977637, 2020). "Preclinical studies designed to address the therapeutic significance of HGF have been performed on injury/disease models, including acute tissue injury, chronic fibrosis, and cardiovascular and neurodegenerative diseases." (PMID 28548072, 2014). "HGF’s ability to inhibit CNS autoimmunity by inducing tolerogenic dendritic cells and regulatory T cells further underscores its therapeutic potential in neurodegenerative diseases." (PMID 39457044, 2024). "The clinical application of immature CiN cells is also promising because HGF may help treat many other neurodegenerative diseases and spinal disorders." (PMID 37762156, 2023). "Thus, NG2 glia-derived HGF may be a critical factor in the development of new therapies for neurodegenerative diseases." (PMID 28195192, 2017). "For example, neurotrophic factors (BDNF, HGF, and VEGF) have been used to prime MSCs in neurodegenerative diseases." (PMID 38167146, 2024).
adenocarcinoma (10 papers, 1998 to 2024). A common cancer characterized by the presence of malignant glandular cells. "This underscores the role of HGF/c-Met signaling pathways in the development of AFP-producing adenocarcinomas, providing a clear link between these pathways and the production of AFP." (PMID 38817451, 2024). "For this, we induced EMT in MDCK cells using HGF and in A549 adenocarcinoma cells using TGF-β." (PMID 37991810, 2024). "This may support the conclusion that autocrine HGF/c-Met activation may induce the dedifferentiation of standard adenocarcinoma cells into a stem cell state to produce AFP or hepatoid differentiation." (PMID 38817451, 2024). "In a co-culture system, we detected a time-dependent increase in miR-21 expression in the HGF-1 fibroblasts when co-cultured with the adenocarcinoma cell line FLO-1 while KYSE-30 cells showed a time-dependent increase of miR-21 expression when co-cultured with HGF-1 fibroblasts." (PMID 24039846, 2013). "This is in agreement with experimental results of wound healing assays in DA3 cells (murine adenocarcinoma), which show an enhanced effect of HGF stimulation on starved cells (no glucose in the medium) compared to cells with 5 mM glucose medium (unpublished data)." (PMID 26337223, 2015).
kidney disease (10 papers, 2011 to 2024). "Cases classified with ACR-7 (renal disorder/LN) were positively associated with FAS but negatively associated with hepatocyte growth factor (HGF)." (PMID 36858042, 2023). "In the IT-PRP group, due to the kidney disease, HGF and TGF- β expression by the kidney decreased and increased, respectively." (PMID 38724923, 2024). "MSC prevented such abatement of HGF/Met, thus saving a system that has been proved to protect the kidney in diverse experimental models of renal disease." (PMID 25277788, 2014). "As a result, inductions of ICAM-1 and E-selectin and leukocyte attachments are suppressed by HGF, contributing to an HGF-mediated improvement in kidney diseases in rodents." (PMID 22536224, 2012). "In addition, a decrease in the expression of HGF compared to TGF- β is related to the progression of kidneys disease." (PMID 38724923, 2024). "We also found, using the Olink proteomic platform, that TNF-α and TMAO enhanced the secretion of additional inflammatory-and growth mediators associated with kidney disease; VEGFA, GDNF, CDCP1, OPG, uPA, AXIN1, MMP-1, MMP-10, PD-L1, HGF, Flt3L, 4E-BP1, CD40, CASP-8, ADA, TNFRSF9, TWEAK44–61." (PMID 38643262, 2024). "but recently observations have suggested that HGF is a potent anti-inflammatory cytokine that inhibits renal inflammation by disrupting nuclear factor (NF)-κB signaling and can be a promising therapeutic agent for progressive renal diseases." (PMID 22531084, 2012).
neurological diseases (9 papers, 2015 to 2024). "Recent studies have shown that HGF acts on neural stem cells to enhance neuronal regeneration and its application in the treatment of neurological disorders has been discussed." (PMID 39768225, 2024). "SHED-CM contains components such as VEGF and HGF, which are known to be effective against neurological diseases, including ALS, and cytokines, such as MCP-1, which promote M1/M2 shift changes." (PMID 39457505, 2024). "SHED-CM contains components such as vascular endothelial growth factor (VEGF) and HGF, which are effective against neurological diseases, including ALS, at much higher levels than bone marrow-derived stem cell CM." (PMID 39457505, 2024). "The possible therapeutic application of HGF and HGF mimetics for the treatment of neurological disorders is discussed." (PMID 34179015, 2021). "In this section, we report some of the most important results reached through HGF or HGF mimetic administration in a panel of animal models of neurological diseases and some outcomes from human clinical trials." (PMID 34179015, 2021). "Topical injections of recombinant HGF have been successfully employed in many animal models of neurological diseases." (PMID 34179015, 2021). "Hepatocyte growth factor promotes beneficial effects in several animal models of neurological diseases, as indicated in the previous paragraph by studies with HGF-secreting stem cell transplantation." (PMID 34179015, 2021). "Hepatocyte growth factor gene transfer in animal models of neurological diseases." (PMID 34179015, 2021). "Administration of HGF and HGF mimetics in animal models of neurological diseases." (PMID 34179015, 2021). "Human clinical trials of HGF-based therapy in neurological diseases." (PMID 34179015, 2021). "Taken together, HGF may be used as the platform or a starting material in developing therapeutics that can provide fundamental treatment methods for a variety of neurological diseases including peripheral neuropathy." (PMID 29844434, 2018). "The findings of the present study suggest that HGF may have multiple roles in these signaling pathways in HCC or in diseases of the nervous system." (PMID 26099202, 2015). "Hence, HGF/MSCs are beneficial to the recovery from nervous system diseases." (PMID 35922965, 2022). "In addition, the production of HGF in the CSF might reflect damage and repair of white matter of the brain and spinal cord in neurologic disease." (PMID 34615471, 2021). "If, by one hand, VEGF and HGF increase vascular permeability contributing to inflammation and nerve damage, and permitting disruption of the blood-brain barrier (BBB), on the other hand, EGF has a neuroprotective role in neurological diseases." (PMID 33776990, 2021).
metabolic disorders (8 papers, 2017 to 2024). "The increased circulation of HGF has been reported to be related to a wide variety of CVDs and metabolic disease." (PMID 37705021, 2023). "The most significant novel shared SNP was rs59950280 (PCPASSOC = 1.33 × 10–10) located near HGFAC, encodes a member of the peptidase S1 protein family, an enzyme activating hepatocyte growth factor (HGF), which further influence metabolic diseases and CVD." (PMID 37705021, 2023). "Based on the current literature and knowledge, it is clear that HGF plays a central role in these metabolic disorders." (PMID 30214428, 2018). "In the context of metabolic diseases, the HGF/MET system has uncertain mixed functions." (PMID 35269415, 2022). "Of note, HGF exerts a pleiotropic action on metabolic disorder." (PMID 28273932, 2017). "NRP-1 serves as a co-receptor to several growth factor (GF) receptors, including vascular endothelial, the hepatocyte and the platelet-derived GF (VEGF, HGF, PDGF, respectively) receptors, all of which are potentially involved in metabolic diseases." (PMID 38638882, 2024).
cardiac disease (6 papers, 2011 to 2023). "On the other hand, excessive HGF/Met signalling in prenatal period may raise adverse effects and might be linked to the pathogenesis of progressive cardiac disease." (PMID 21347410, 2011). "Taken together, our data show that excessive activation of the HGF/Met system in development may result in cardiac damage and suggest that Met signalling may be implicated in the pathogenesis of cardiac disease." (PMID 21347410, 2011). "It has been reported that the modification of the HGF gene is beneficial to the therapeutic efficacy of MSCs, including diseases of the heart, lung, liver, urinary system, bone and skin, lower limb ischaemia and immune‐related diseases." (PMID 35922965, 2022). "Furthermore, we address the meaning of elevated HGF in the context of acuteness of cardiac diseases." (PMID 28548070, 2014). "Finally, we examine the potential of HGF-based molecules as new therapeutic tools for the treatment of cardiac diseases." (PMID 28548070, 2014). "Furthermore, we discuss the putative role of elevated HGF as prognostic marker of severity in patients with cardiac diseases." (PMID 28548070, 2014).